SAMD1 (sterile alpha motif domain containing 1)
Description:
Unmethylated CpG islands (CGIs)-binding protein which localizes to H3K4me3-decorated CGIs, where it acts as a transcriptional repressor. Tethers L3MBTL3 to chromatin and interacts with the KDM1A histone demethylase complex to modulate H3K4me2 and H3K4me3 levels at CGIs. Plays a role in atherogenesis by binding with LDL on cell surface and promoting LDL oxidation which leads to the formation of foam cell.
Gene: Protein-coding gene on chromosome 19 (14,087,851 to 14,091,036, reverse strand). Ensembl gene ENSG00000141858.
Subcellular location: Nucleus; Chromosome; Secreted
Subcellular location (Human Protein Atlas): Nucleoplasm; Mitotic chromosome
Genetic constraint (gnomAD): Loss-of-function variants: 11 observed, 23.81 expected, observed/expected ratio (o/e) 0.46, 90% interval 0.29 to 0.76. The synonymous counts are far from expectation, so gnomAD's model fits this gene poorly and the ratio says little. Missense variants: 470 observed, 364.65 expected, observed/expected ratio (o/e) 1.29, 90% interval 1.19 to 1.39. Synonymous variants: 269 observed, 161.49 expected, observed/expected ratio (o/e) 1.67, 90% interval 1.51 to 1.84.
Homologues: Orthologues: chimpanzee SAMD1 (77% identical), zebrafish samd1a (29% identical), zebrafish si:ch211-230g15.5 (14% identical), zebrafish phc3 (1% identical). Paralogues in human: SFMBT1 (17% identical), SFMBT2 (17% identical), SCML2 (16% identical), SCMH1 (15% identical), PHC3 (14% identical), PHC1 (13% identical), L3MBTL4 (13% identical), L3MBTL3 (13% identical), SAMD13 (12% identical), PHC2 (12% identical), L3MBTL1 (12% identical), SCML4 (11% identical), and 6 more.
Diseases named in the same sentence as SAMD1 in open-access papers:
SAMD1 is named in the same sentence as 20 diseases in open-access papers, as found by Europe PMC text mining. Sharing a sentence is not in itself a finding about the gene and the disease. The quoted sentences say what the papers report.
atherosclerosis (5 papers, 2021 to 2023). A disease characterized by the build-up of fatty material and calcium deposition in the arterial wall resulting in partial or complete occlusion of the arterial lumen. "SAM domain-containing protein 1 (SAMD1) has been implicated in atherosclerosis, as well as in chromatin and transcriptional regulation, suggesting a versatile and complex biological function." (PMID 36810619, 2023). "SAM domain containing 1 (SAMD1) is a repressive chromatin regulator and predicted transcriptional repressor, which is implicated in atherosclerosis through binding with LDL on cell surface and promoting LDL oxidation which contributes to the formation of foam cells." (PMID 37904675, 2023). "Together, we uncovered a novel mechanism whereby miR-378c-Samd1 circuit participates in two key elements of atherosclerosis, VSMCs phenotypic transition and LDL oxidation." (PMID 34006929, 2021). "Here, we report that miR-378c protects against atherosclerosis by directly targeting Sterile Alpha Motif Domain Containing 1 (Samd1), a predicted transcriptional repressor." (PMID 34006929, 2021). "It is very intriguing that we identified Samd1 as a previously unrecognized transcriptional repressor that plays a vital role in the development of atherosclerosis." (PMID 34006929, 2021). "Collectively, our finding provides a potential rationale to target miR-378c-Samd1 pathway for the detection and treatment of atherosclerosis." (PMID 34006929, 2021). "It was an unexpected finding, given that SAMD1 has been described to be secreted and to be involved in Atherosclerosis." (PMID 34136100, 2021). "Our results provided a better understanding of atherosclerosis pathophysiology and potential therapeutic management by targeting miR-378c-Samd1 circuit." (PMID 34006929, 2021).
liver cancer (3 papers, 2022 to 2024). An epithelial or non-epithelial malignant neoplasm that arises from the liver. "Our work demonstrated that SAMD1 is commonly upregulated in liver cancer and that its high expression is associated with poor prognosis in this cancer type." (PMID 35453756, 2022). "To gain insight into the molecular mechanisms of liver cancer cells, we assessed the role of the CpG island regulator SAMD1, which is highly expressed in liver cancer tissues and associated with poor prognosis." (PMID 35453756, 2022). "Importantly, the investigation of common signatures that have been associated with good or poor prognosis suggests that SAMD1 deletion alters the transcriptional network towards a signature that would be preferable for liver cancer patients." (PMID 35453756, 2022). "In some cancer types, high SAMD1 expression correlates with poor prognoses, such as in liver cancer (LIHC) and kidney renal clear cell carcinoma (KIRC), indicating a more oncogenic role." (PMID 39137238, 2024). "In multiple tumor types, SAMD1 expression is up-regulated, and in liver cancer cells, knockout of SAMD1 has been shown to reduce proliferation and clonogenicity." (PMID 39137238, 2024). "Taken together, these data suggest that high SAMD1 expression in liver cancer cells is involved in establishing an unfavorable transcriptional network that contributes to worse prognosis for HCC patients." (PMID 35453756, 2022). "One of the strongest increases in SAMD1 expression in tumor versus normal tissues was found in liver cancer." (PMID 35453756, 2022). "Given the detectable expression of SAMD1 in HepG2 liver cancer cells, these cells were selected as our experimental model for further investigations." (PMID 35453756, 2022). "In the present study, we aimed to gain the first insights into the role of SAMD1 in human cancer cells, with a focus on the hepatocellular carcinoma cell line HepG2, which is a commonly used liver cancer cell line and where SAMD1 is strongly expressed." (PMID 35453756, 2022). "To address the role of SAMD1 in liver cancer, we used the commonly applied HepG2 cell line, in which SAMD1 can easily be detected via Western blotting." (PMID 35453756, 2022). "Moreover, liver cancer patients with high levels of SAMD1 exhibit a more unfavorable transcriptional network." (PMID 39137238, 2024). "Inhibiting SAMD1’s function in liver cancer cells may therefore lead to a more favorable gene signature." (PMID 35453756, 2022). "SAMD1 knockout HepG2 cells showed a slightly reduced proliferation rate, consistent with the hypothesis that SAMD1 contributes to liver cancer cell proliferation." (PMID 35453756, 2022). "Using previously curated datasets of liver cancer patients, we found that gene sets expressed in hepatocellular carcinoma patients with poorer prognosis become predominantly downregulated in SAMD1 KO HepG2 cells, while genes that are expressed in HCC patients with better survival become upregulated." (PMID 35453756, 2022). "Using HepG2 cells, we addressed the question of how the upregulation of SAMD1 in liver cancer may contribute to liver cancer progression and poor prognosis." (PMID 35453756, 2022). "Interfering with SAMD1’s function may be suitable to shift liver cancer cells towards a more favorable setup, which could provide a new strategy for the treatment of liver cancer patients." (PMID 35453756, 2022). "Thus, high SAMD1 expression could contribute to an augmentation of the mTOR signaling pathway in liver cancer cells, which may lead to enhanced cell growth." (PMID 35453756, 2022). "In addition to liver cancer, SAMD1 is upregulated in many other human cancer types, suggesting that SAMD1 could play a pivotal role in various cancers." (PMID 35453756, 2022).
liver cancer (continued). "Thus, this work supports that interfering with SAMD1’s function in human liver cancer cells could be a valid treatment option for hepatocellular carcinomas." (PMID 35453756, 2022). "Since the role of SAMD1 in cancer has not yet been explored, we decided to investigate the cellular function of SAMD1 in liver cancer cells in greater detail." (PMID 35453756, 2022).
thymoma (2 papers, 2022 to 2024). A neoplasm arising from the epithelial cells of the thymus. "Similar results were also obtained for thymoma and cervical cancer, where high SAMD1 expression also correlates with a better prognosis." (PMID 39137238, 2024). "In some other cancer types, such as cervical cancer (CESC) and thymoma (THYM), high SAMD1 expression correlates with a better prognosis, suggesting a more tumor-suppressive role." (PMID 39137238, 2024). "These opposing roles of SAMD1 and FBXO11 can also be seen for other cancer types, such as thymoma and cervical cancer." (PMID 39137238, 2024).
adenoid cystic carcinoma (1 paper, 2021). A malignant tumor arising from the epithelial cells. "For example, SAMD1 expression has a strong prognostic value for ACC (adenoid cystic carcinoma) patients, further supporting a role of SAMD1 in cancer." (PMID 34136100, 2021).
antiphospholipid syndrome (1 paper, 2023). A disorder caused by the presence of autoantibodies directed against phospholipids, causing a hypercoaguable state, which may result in blood clots, stroke, heart attack, and in women, significant pregnancy-related complications, including miscarriage and still birth. "This study was intended to investigate the effect of SAMD1 on antiphospholipid syndrome (APS)‐induced pregnancy complications in mice." (PMID 37904675, 2023).
hepatocellular carcinoma (1 paper, 2022). A malignant tumor that arises from hepatocytes. "Here, we used the hepatocellular carcinoma cell line HepG2 as a cancer model and investigated the cellular and transcriptional roles of SAMD1 using ChIP-Seq and RNA-Seq." (PMID 35453756, 2022). "Our work suggests that SAMD1 is involved in establishing a pro-proliferative setting in hepatocellular carcinoma cells." (PMID 35453756, 2022). "Taken together, these experiments support the model in which SAMD1 acts as a negative regulator of PIK3IP1 in wild-type HepG2 cells, which is a negative regulator of PI3K in hepatocellular carcinoma cells." (PMID 35453756, 2022).
kidney cancer (1 paper, 2024). Primary or metastatic malignant neoplasm involving the kidney. "In contrast, the opposite is the case in cancer types where high SAMD1 correlates with a worse prognosis, such as kidney cancer." (PMID 39137238, 2024).
pancreatic cancers (1 paper, 2024). "Primarily, most of the work was conducted using human pancreatic ductal adenocarcinoma cell lines, which provide limited insights into the potentially more complex role of SAMD1 in pancreatic cancers in patients." (PMID 39137238, 2024). "In the context of pancreatic cancer cells, such a mechanism may be essential to overcome the tumor-suppressive function of SAMD1." (PMID 39137238, 2024). "Consequently, the level of SAMD1 expression in pancreatic cancer samples at the time of diagnosis could potentially serve as a predictive marker for disease progression." (PMID 39137238, 2024). "While our biochemical studies indicate that FBXO11 inhibits the chromatin binding of SAMD1, the precise molecular mechanisms and how FBXO11 influences the biological role of SAMD1 in pancreatic cancer have not been fully elucidated in this study." (PMID 39137238, 2024).
thrombosis (1 paper, 2023). "SAMD1 expression was low in serum of APS patients, which was correlated with the history of thrombosis and the number of adverse pregnancies." (PMID 37904675, 2023).
cancer (4 papers, 2021 to 2024). A tumor composed of atypical neoplastic, often pleomorphic cells that invade other tissues. "The expression of SAMD1 positively correlates with the expression of common proliferation markers, suggesting that high SAMD1 levels are associated with higher aggressiveness of cancer." (PMID 35453756, 2022). "The difference in survival becomes particularly evident at later time points, suggesting that a high SAMD1 expression level prevents an adverse cancer progression over time." (PMID 39137238, 2024). "Although our experiments suggest that SAMD1 suppresses EMT-pathway genes in cancer cells, the role of SAMD1 in the development of metastases in patients remains to be explored in further detail." (PMID 39137238, 2024). "Our work suggests that FBXO11 inhibits SAMD1 chromatin association, which represents a novel regulatory mechanism of FBXO11 in cancer." (PMID 39137238, 2024). "Analysis of patient data revealed that SAMD1 is frequently dysregulated in cancer, and its expression often correlates with favorable or unfavorable prognoses." (PMID 39137238, 2024). "Investigation of public cancer gene expression data from TCGA showed that SAMD1 is commonly up-regulated in cancer." (PMID 39137238, 2024). "GSEA analysis of the RNA-seq data demonstrated that the deletion of SAMD1 leads to the dysregulation of multiple cancer-related pathways." (PMID 39137238, 2024). "After deleting SAMD1 in PDAC cell lines, we observed increased migration rates and up-regulation of cancer-associated pathways, including the EMT pathway." (PMID 39137238, 2024). "SAMD1 is often upregulated in cancer tissues and correlates with worse prognosis in some cancer types, such as adenoid cystic carcinoma (ACC) and liver cancer." (PMID 36810619, 2023). "Both public data and Western blotting experiments suggest that the SAMD1 protein is abundantly expressed in most human cancer cell lines." (PMID 35453756, 2022). "The investigation of public cancer gene expression data from TCGA showed that the SAMD1 transcript is mostly upregulated in cancerous tissues compared to normal tissues." (PMID 35453756, 2022). "A vital cancer type in which high SAMD1 expression correlates with a better prognosis is PDAC." (PMID 39137238, 2024). "Together, these data support the hypothesis that in PDAC, and perhaps other cancer types, the tumor-suppressive function of SAMD1 is counteracted by FBXO11." (PMID 39137238, 2024). "Enhanced cellular migration, but no change of proliferation, could also be found in BxPC3 PDAC cancer cells upon SAMD1 deletion." (PMID 39137238, 2024). "In the context of other cancer types, the role of SAMD1 remains largely unexplored." (PMID 39137238, 2024). "We hypothesized that gaining a deeper understanding of the potential tumor-suppressive role of SAMD1 in PDAC may allow us to employ this function to limit cancer growth." (PMID 39137238, 2024). "Further work is required to fully comprehend SAMD1’s role in liver and other cancer types." (PMID 35453756, 2022). "Thus, it will be of interest to further decipher the molecular mechanisms of SAMD1’s repressive function in human cancer cells in future studies." (PMID 35453756, 2022). "In the future, it will also be of interest to address whether SAMD1 plays a role in other human cancer cell types and to analyze its involvement during tumor onset." (PMID 35453756, 2022). "An increased expression of SAMD1 in several cancer tissues can be found, which may suggest a role of SAMD1 in cancer." (PMID 34136100, 2021). "Thus, it is currently unknown why SAMD1 has these potentially opposing roles in different cancer types." (PMID 39137238, 2024). "Together, our study offers novel insights into the control of EMT-related genes in PDAC, revealing the intricate involvement of SAMD1 and its interplay with FBXO11 in this cancer type." (PMID 39137238, 2024).
cancer (continued). "In summary, our findings provide insights into the regulation of EMT-related genes in PDAC, shedding light on the intricate role of SAMD1 and its interplay with FBXO11 in this cancer type." (PMID 39137238, 2024). "More research will be necessary to clarify the detailed processes of how the FBXO11 E3 ubiquitin ligase complex influences SAMD1 function in the cells, and how this role contributes to the overall function of FBXO11 in cancer cells." (PMID 39137238, 2024). "Together, these observations lead to the hypothesis that in some cancer types, such as PDAC, SAMD1 may be involved in repressing EMT pathways, thereby inhibiting metastasis, which in turn may contribute to a better outcome." (PMID 39137238, 2024). "The unmethylated CpG island-binding protein SAMD1 is upregulated in many human cancer types, but its cancer-related role has not yet been investigated." (PMID 35453756, 2022). "Interestingly, the distinct relationships to patient survival do not correlate with changes in SAMD1 gene expression upon tumorigenesis, given that SAMD1 has increased expression in most cancer tissues compared to normal tissues." (PMID 39137238, 2024). "Notably, given conflicting gene annotations, the human SAMD1 gene has not been included in comprehensive CRISPR screening experiments that investigated the role of most human genes in human cancer cell lines." (PMID 35453756, 2022). "Notably, in all investigated cancer types, high SAMD1 expression correlates with high expression of MYC target genes, independent of whether high SAMD1 expression is favorable or unfavorable, suggesting that this feature is not predictive." (PMID 39137238, 2024).
tumor (3 papers, 2022 to 2025). "Taken together, our work unveiled a tumor-suppressive role of SAMD1 in PDAC through inhibiting EMT-related genes." (PMID 39137238, 2024). "During this work, we noticed a decreased chromatin binding of SAMD1 in PDAC cell lines compared to other tumor cell lines." (PMID 39137238, 2024). "The repression of CDH2 may therefore be a key element of SAMD1’s tumor-suppressive role in PDAC." (PMID 39137238, 2024). "From TCGA tumor expression data via GEPIA2, the top 100 genes positively correlated with LRFN4 expression were determined, among which TPX2 (R = 0.36), KIF18B (R = 0.39), RCE1 (R = 0.53), PCNXL3 (R = 0.49), and SAMD1 (R = 0.48) showed significant correlations (P < 0.001)." (PMID 40386777, 2025).
SAMD1 also shares sentences with these, for which no sentence is quoted: cervical cancer (1 paper); cholangiocarcinoma (1); diffuse large B-cell lymphoma (1); head and neck squamous cell carcinoma (1); ovarian serous cystadenocarcinoma (1); pancreatic adenocarcinoma (1); pancreatic ductal adenocarcinoma (1); prostate carcinoma (1); sarcoma (1).